H3P16 (H3 histone pseudogene 16)
Synonyms: p21; H3.6; formerly H3F3AP6
Gene: Processed pseudogene on chromosome 4 (139,698,144 to 139,698,554, reverse strand). Ensembl gene ENSG00000178458.
Diseases named in the same sentence as H3P16 in open-access papers:
H3P16 is named in the same sentence as 1 disease in open-access papers, as found by Europe PMC text mining. Sharing a sentence is not in itself a finding about the gene and the disease.
H3P16 shares sentences with these, for which no sentence is quoted: ischemic stroke (1 paper).